Y_RNA (Y RNA )
Gene: Miscellaneous RNA gene on chromosome 17 (64,390,158 to 64,390,263, reverse strand). Ensembl gene ENSG00000239823.
Homologues: Orthologues: chimpanzee Y_RNA (100% identical), macaque Y_RNA (86% identical), guinea pig Y_RNA (79% identical), guinea pig Y_RNA (77% identical), guinea pig Y_RNA (75% identical). Paralogues in human: Y_RNA (80% identical), Y_RNA (79% identical), RNY1P7 (78% identical), Y_RNA (78% identical), Y_RNA (77% identical), RNY1 (76% identical), Y_RNA (76% identical), RNY1P10 (75% identical), Y_RNA (75% identical), RNY1P5 (75% identical), RNY1P11 (74% identical), Y_RNA (74% identical), and 88 more.